RBBP6 (RB binding protein 6, ubiquitin ligase)
Description:
E3 ubiquitin-protein ligase which promotes ubiquitination of YBX1, leading to its degradation by the proteasome. Regulates DNA-replication and the stability of chromosomal common fragile sites (CFSs) in a ZBTB38- and MCM10-dependent manner. Controls ZBTB38 protein stability and abundance via ubiquitination and proteasomal degradation, and ZBTB38 in turn negatively regulates the expression of MCM10 which plays an important role in DNA-replication. (Microbial infection) [Isoform 1]: Restricts ebolavirus replication probably by impairing the vp30-NP interaction, and thus viral transcription.
Synonyms: RBQ-1; PACT; My038; P2P-R; SNAMA
Tractability: PROTAC: UniProt records ubiquitination sites on it; ubiquitination databases record sites on it; its protein half-life has been measured.
Gene: Protein-coding gene on chromosome 16 (24,537,693 to 24,572,863, forward strand). Ensembl gene ENSG00000122257.
Subcellular location: Nucleus, nucleolus; Chromosome; Cytoplasm, cytoskeleton, microtubule organizing center, centrosome
Subcellular location (Human Protein Atlas): Nuclear speckles
Pathways (Reactome):
Immune System: Antigen processing: Ubiquitination & Proteasome degradation
Metabolism of RNA: mRNA Polyadenylation
Signal Transduction: RHOBTB1 GTPase cycle
Gene Ontology:
Molecular function: protein binding; protein kinase binding; RNA binding; ubiquitin protein ligase activity; ubiquitin-protein transferase activity; nucleic acid binding; zinc ion binding
Biological process: DNA damage response; regulation of DNA replication; ubiquitin-dependent protein catabolic process; co-transcriptional mRNA 3'-end processing, cleavage and polyadenylation pathway; mRNA processing; protein ubiquitination
Cellular component: centrosome; nuclear speck; protein-containing complex; cytosol; nucleoplasm; chromosome; nucleolus
Genetic constraint (gnomAD): Loss-of-function variants: 25 observed, 164.89 expected, observed/expected ratio (o/e) 0.15, 90% interval 0.11 to 0.21. The upper end of that interval is the gene's LOEUF score, 0.21, which puts it in group 1 of 6, group 1 being the genes least tolerant of losing a copy. Missense variants: 1,851 observed, 2,201.9 expected, observed/expected ratio (o/e) 0.84, 90% interval 0.81 to 0.87. Synonymous variants: 781 observed, 760.94 expected, observed/expected ratio (o/e) 1.03, 90% interval 0.97 to 1.09.
Homologues: Orthologues: chimpanzee RBBP6 (99% identical), macaque RBBP6 (99% identical), dog RBBP6 (95% identical), rabbit RBBP6 (94% identical), pig RBBP6 (93% identical), guinea pig RBBP6 (91% identical), rat Rbbp6 (89% identical), mouse Rbbp6 (89% identical). Paralogues in human: ZCCHC24 (4% identical).
Diseases named in the same sentence as RBBP6 in open-access papers:
RBBP6 is named in the same sentence as 41 diseases in open-access papers, as found by Europe PMC text mining. Sharing a sentence is not in itself a finding about the gene and the disease. The quoted sentences say what the papers report.
cervical cancer (7 papers, 2014 to 2024). A primary or metastatic malignant neoplasm involving the cervix. "In this article, FISH also showed that RBBP6 variants 1 and 2 are lost as cervical cancer progresses." (PMID 30886526, 2019). "Using fluorescent in situ hybridization (FISH), RBBP6 variants were found to be abundantly transcribed in cervical cancer cases." (PMID 30886526, 2019). "In the present study, we demonstrated the potential role of RBBP6 expression on the sensitivity of cervical cancer (CC) cells to cisplatin chemotherapy." (PMID 38667315, 2024). "In fact, the reduction in apoptosis induction following co-treatment with siRBBP6 and cisplatin suggests that RBBP6 is necessary for the sensitization of cervical cancer cells to cisplatin." (PMID 38667315, 2024). "RBBP6 expression was knocked down successfully in human cervical cancer cells using RNA interference technology." (PMID 38667315, 2024). "This study stands among the pioneering investigations to document the role of RBBP6 in the response of cervical cancer cells to CDDP." (PMID 38667315, 2024). "RBBP6 expression significantly correlated with apoptotic levels and was indirectly proportional to Ki67 in human cervical cancers." (PMID 30886526, 2019). "In this study, we also found high levels of Bcl-2 in cervical cancer lesions where RBBP6 expression was low." (PMID 30886526, 2019). "Because of the high expression and corresponding pro-apoptotic activity observed in cervical cancer cells in this study, we suggest that RBBP6 is involved in the malignant progression of cervical cancer." (PMID 30886526, 2019). "The aim of this study was to establish expression levels and tissue distribution of the RBBP6 gene products at both protein and messenger RNA (mRNA) levels in cervical cancer by immunocytochemistry and in situ hybridization (ISH)." (PMID 30886526, 2019). "This is the first report on the abundant expression of RBBP6 in cervical cancer and its involvement in the malignant progression of cervical cancer." (PMID 30886526, 2019). "There were increased levels of RBBP6 in cervical cancers in contrast to normal tissues suggesting that RBBP6 is involved in cervical cancer pathogenesis." (PMID 30886526, 2019). "RBBP6 was upregulated in the undifferentiated cervical cancer grades in contrast to normal tissue sections." (PMID 30886526, 2019). "Image analysis indicated upregulation of RBBP6 by a mean factor of 8.073 (P = .0001) in cervical carcinoma cell lines (HeLa) as compared with a normal lung cell line (MRC-5)." (PMID 30886526, 2019). "Up-regulation of RBBP6 has been strongly correlated with tumor progression in esophageal cancer and cervical cancer." (PMID 25379943, 2014). "In a number of malignancies, including oesophageal cancer, breast cancer, lung cancer, and cervical cancer, retinoblastoma-binding protein 6 (RBBP6), which regulates cell proliferation, cell cycle, and cell apoptosis, is greatly up-regulated and is associated with poor clinical prognosis." (PMID 36853473, 2023).
cervical cancer (continued). "The RBBP6 mRNA was also upregulated in cervical cancer in contrast to the normal cervical tissue." (PMID 30886526, 2019). "RBBP6 proteins can therefore be targeted for therapeutic interventions against cervical cancer." (PMID 30886526, 2019). "This further suggests an involvement of RBBP6 in cervical cancer development." (PMID 30886526, 2019). "A link between RBBP6 expression, apoptosis, and cervical cancer progression was also investigated." (PMID 30886526, 2019). "Cervical cancer was found to have dysregulation in two ATTS regulatory factors: cold-inducible RNA binding protein (CIRP, also known as CIRBP or A18 hnRNP), which binds and stabilizes pro-survival gene transcripts, and RBBP6, which suppresses polyadenylation." (PMID 37176052, 2023). "The expression of RBBP6 has been documented in several cancers but RBBP6 expression in cervical cancer has not been well studied." (PMID 30886526, 2019). "Qualitatively, FISH studies showed elevated levels of the three RBBP6-mRNA transcripts in cervical cancer as compared with the normal tissues." (PMID 30886526, 2019).
breast carcinoma (3 papers, 2018 to 2023). "This study further showed that arsenic trioxide and curcumin lowered the expression of the RBBP6 splice variant 1 in MCF-7 breast cancer cells." (PMID 31534777, 2019). "Little is known about the expression and regulation of human RBBP6 splice variants during cell cycle progression and breast cancer development." (PMID 31534777, 2019). "Little is known about the expression and regulation of the human RBBP6 splice variants by arsenic trioxide during cell cycle progression and breast cancer development." (PMID 31534777, 2019). "In this study, we have shown that breast cancer cells may have lost the expression of RBBP6 variants 2 and 3 in favor of the carcinogenesis process." (PMID 31534777, 2019). "On the other hand, the smaller RBBP6 variant 3 might be involved in the regulation of cell cycle arrest, especially G2/M cell cycle arrest as previously shown in kidney embryonic cells, which was undetectable in breast cancer cells." (PMID 31534777, 2019). "This study explores the possible involvement of RBBP6 transcripts in breast cancer development and their roles in the regulation of cell cycle and apoptosis." (PMID 31534777, 2019). "The expression of the RBBP6 transcripts is not fully understood, especially during cell cycle arrest and apoptosis in breast cancer." (PMID 31534777, 2019). "RBBP6 was overexpressed in breast cancer tissues that were classified as stages 3 and 4, while in stage 1, its expression was much lower." (PMID 30237738, 2018). "The sections of breast cancer of the ductus and lumina showed strong cytoplasmic expression of RBBP6 protein, but weaker expression in the nucleus of tumor cells." (PMID 30237738, 2018). "Successful silencing and overexpression of RBBP6 have enabled the understanding of the effects of RBBP6 on both breast cancer cell lines." (PMID 30237738, 2018). "Following the analysis at mRNA and protein levels in breast cancer tissue, RBBP6 expression was successfully manipulated using gene silencing and protein overexpression techniques in MCF-7 and MDA-MB-231 cell lines." (PMID 30237738, 2018). "In this paper, the analysis of RBBP6 transcripts during cell cycle arrest and apoptosis was carried out to assess the possible involvement of RBBP6 variants in the carcinogenesis process, using MCF-7 breast cancer cells." (PMID 31534777, 2019). "Downregulation of cell cycle regulatory biomolecules favors the carcinogenesis process, hence downregulation of RBBP6 variant 3 in breast cancer is not surprising." (PMID 31534777, 2019). "Both cytotoxic agents were therefore suitable for studying the expression of RBBP6 transcripts during cell cycle arrest and apoptosis of MCF-7 breast cancer cells." (PMID 31534777, 2019). "We have reported that both the breast cancer cell lines, MCF-7 and MDA-MB-231, respond to RBBP6 silencing by differentially ceasing to grow, whereas overexpression of RBBP6 maintains their increase in proliferation." (PMID 30237738, 2018).
colon cancer (3 papers, 2013 to 2019). "Furthermore, RBBP6 was identified as a strong marker for colon cancer prognosis and as a predisposing factor in familial myeloproliferative neoplasms." (PMID 25955646, 2015). "These strong associations suggest that RBBP6 overexpression promotes tumor invasion and metastasis and that RBBP6 could possibly be used as a biomarker for a more aggressive phenotype of colon cancer." (PMID 23799110, 2013). "RBBP6 was highly expressed in 103 of 180 (57.2%) colon tumor tissues compared with 62 of 180 (34.4%) adjacent normal mucosae tissues." (PMID 31685801, 2019). "The human retinoblastoma binding protein 6 (RBBP6) is implicated in esophageal, lung, hepatocellular and colon cancers." (PMID 25955646, 2015). "The frequent up-regulation of RBBP6 expression in human colon cancer highlights its potential as a novel therapeutic target for this cancer." (PMID 23799110, 2013). "Of the 40 colon cancer samples, 4 showed strong up-regulation of RBBP6 mRNA expression that was determined by qPCR, and the RBBP6 protein expression in the 4 samples was evaluated by western blot analysis." (PMID 23799110, 2013). "In summary, this study provided critical insight into the role of the RBBP6 gene in the progression of colon cancer." (PMID 23799110, 2013). "The results of the present study showed that positive RBBP6 staining was considerably higher in metastatic colon cancer cells within lymph nodes than in the paired primary tumors." (PMID 23799110, 2013). "Furthermore, RBBP6 was identified as an independent prognostic marker for overall and for disease-free survival in colon cancer patients." (PMID 25955646, 2015). "Although limitations include the small number of patients with relatively short follow-up time, our results provide the first evidence that RBBP6 could be used as a novel biomarker for improved outcome after colectomy in patients with colon cancer." (PMID 23799110, 2013). "Therefore, quantitative real-time PCR and western blot analyses were performed to detect RBBP6 expression in colon cancer tissues." (PMID 23799110, 2013). "We compared RBBP6 expression between CRC tissues and adjacent normal tissues in relation to CRC pathogenesis in TCGA dataset, GEO dataset and 180 colon cancer patients from Shanghai General Hospital." (PMID 31685801, 2019). "The human retinoblastoma binding protein 6 (RBBP6) is overexpressed in esophageal, lung, hepatocellular and colon cancers." (PMID 25955646, 2015). "Among the 40 paired specimens subject to qPCR analysis, 24 (60%) colon cancers showed at least a 2-fold increase in RBBP6 mRNA levels compared with that of the adjacent non-cancerous tissues." (PMID 23799110, 2013).
esophageal cancer (3 papers, 2014 to 2026). A primary or metastatic malignant neoplasm involving the esophagus. "RBBP6 is overexpressed in several types of tumors, including lung, colorectal, breast, cervical, hepatocellular, and esophageal cancers, suggesting its association with malignant progression." (PMID 42239902, 2026). "Some lines of evidence showed that the enhanced expression of different RBBP6 variants correlate with poor clinical prognosis in colon, prostate and esophageal cancer." (PMID 31534777, 2019).
colorectal cancer (2 papers, 2018 to 2019). A primary or metastatic malignant neoplasm that affects the colon or rectum. "Further studies were reported in cervical and colorectal cancers with RBBP6 overexpressed in well-differentiated cancers." (PMID 30237738, 2018). "Interestingly, here we show that RBBP6 is upregulated in colorectal cancer (CRC) where its expression level is positively correlated with distant metastasis." (PMID 31685801, 2019).
deafness (2 papers, 2015 to 2021). An inherited or acquired condition characterized by the complete loss of the ability to hear from one or both ears. "USP31 and RBBP6 have been shown to be strongly associated with late onset deafness in border collies." (PMID 26664958, 2015).
gastric cancer (2 papers, 2014 to 2023). A primary or metastatic malignant neoplasm involving the stomach. "IHC analysis also indicated that RBBP6 expression was associated with invasion depth, LN metastasis, distant metastasis, and a poor prognosis in gastric cancer patients." (PMID 25379943, 2014). "Following univariate analysis, RBBP6, DCTPP1, HSPA4, and ALDOA expression levels were significantly associated with poor prognosis in 300 gastric cancer patients." (PMID 25379943, 2014). "RBBP6, DCTPP1, HSPA4, and ALDOA expression in particular were significantly associated with a poor prognosis in the 300 gastric cancer patients." (PMID 25379943, 2014). "The result of the study provided evidence that eight proteins (ALDOA, DCTPP1, GLG1, HSPA4, KRT18, VPS13A and RBBP6) may be potential cancer stem cell markers of gastric cancer." (PMID 38328436, 2023). "In particular, RBBP6 may be a promising predictive marker for the prognosis of patients with gastric cancer." (PMID 25379943, 2014). "RBBP6, DCTPP1, and HSPA9 were observed to be primarily expressed in the cytoplasm and nuclei of gastric cancer cells." (PMID 25379943, 2014).
lung carcinoma (2 papers, 2018 to 2023). "Similar results were reported by Motadi et al12 in which RBBP6 was highly expressed in stage IV lung cancer, while in stages II and I, lower expression was observed." (PMID 30237738, 2018).